GSDME (gasdermin E)
Diseases named in the same sentence as GSDME in open-access papers (continued):
Sharing a sentence is not in itself a finding about the gene and the disease.
lung carcinoma (continued). "Cisplatin induced higher levels of secondary necrosis/pyroptosis than paclitaxel in A549 cells, suggesting that cisplatin may provide additional advantages in treating lung cancers with high levels of GSDME expression." (PMID 40721578, 2025). "Additionally, it has been reported that both paclitaxel and cisplatin can activate the caspase-3/GSDME pathway, shifting the cell death process from apoptosis to pyroptosis, thus suppressing lung cancer cell proliferation." (PMID 38756442, 2024). "Moreover, nitidine chloride substantially inhibited the PI3K/AKT pathway transduction and induced pyroptosis of tumor cells in vivo, indicating that nitidine chloride is a potential drug for lung cancer by inducing GSDME-dependent pyroptosis." (PMID 38104141, 2023). "Similarly, it has been shown that high expression of GSDME can improve the sensitivity of lung cancer cells to drugs." (PMID 38016064, 2023). "Recent mechanistic work revealed that GSDME knockdown can trigger the transition from apoptosis-to-pyroptosis in lung cancer lines, confirming the hypothesis that GSDME expression determines the type of cell death in caspase-3-activated tumor cells." (PMID 38104141, 2023). "Paclitaxel and cisplatin induce apoptosis via caspase-3/GSDME activation in A549 lung cancer cells." (PMID 37061535, 2023). "Furthermore, we found that tissues from lung cancer patients with higher GSDME expression had fewer lymph node metastases." (PMID 34553845, 2022). "In addition, the expression level of GSDME was positively correlated with that of caspase-3, and hence caspase-3 is also an important prognostic biomarker in lung cancer patients." (PMID 36523974, 2022). "Compared to paired normal lung tissues, the expressions of GSDME, caspase-3, and caspase-8 were significantly were increased in most lung cancer tissues, and GSDME was mainly found in the cytoplasm and a small amount in the cell membrane in lung cancer tissues." (PMID 36523974, 2022). "According to a previous study, chemotherapy drugs paclitaxel and cisplatin were beneficial to patients with lung cancer since they could activate caspase-3/GSDME to promote pyroptosis of cancer cells." (PMID 35281845, 2022). "In addition, we also analyzed the effect of myricetin on the mouse lung cancer Lewis cells and found that myricetin can also lead to their pyroptosis by activating caspase-3-mediated cleavage of GSDME." (PMID 36091790, 2022). "The goal of this study was to determine whether the expression levels of caspase‐3 and GSDME affect the clinical stage, pathological grade, or survival prognosis of patients with lung cancer." (PMID 34553845, 2022). "In addition, we also analyzed the effect of myricetin on the mouse lung cancer Lewis cells and found that myricetin can also lead to pyroptosis by activating caspase-3-mediated cleavage of GSDME." (PMID 36091790, 2022). "GSDME is cleaved by cleaved-caspase-3 to generate GSDME-N, where GSDME-N can directly oligomerize, release LDH, and cause plasma membrane lysis, leading to lung cancer pyroptosis." (PMID 36091790, 2022). "The expression of GSDME was detected in human lung cancer cells." (PMID 33634141, 2021). "Furthermore, evidence proved that cisplatin-induced a high degree of pyroptosis in lung cancer cells through the caspase-3/GSDME pathway." (PMID 34731088, 2021). "The basal expression of GSDME in 15 human tumor cell lines, derived from lung cancer (A549, PC9, H322, H1299, and SPCA-1), gastric cancer (HGC27, MKN28, MGC803, BGC823 and SGC7901) and liver cancer (MHCC97L, Bel7402, QGY7703, HepG2, and SMMC7721), were determined." (PMID 32341339, 2020).
lung carcinoma (continued). "Recent study found that cisplatin induced pyroptotic cell death in lung cancer cells by targeting Caspase-3/Gasdermin E (GSDME) signaling cascade, nevertheless, it is still unclear whether cisplatin induced GC cell pyroptosis." (PMID 32516127, 2020). "In addition, cisplatin may provide significant benefits in the treatment of lung cancers with high GSDME expression." (PMID 37752941, 2023). "Accordingly, GSDME-induced pyroptosis may play an important role in lung cancer." (PMID 35819638, 2022). "GSDME may be an independent factor affecting the prognosis of patients with lung cancer." (PMID 34553845, 2022). "Based on the univariate and multivariate analyses, we found that the high expression level of GSDME in lung cancer tissues was associated with longer postoperative survival time, indicating that GSDME may be an independent factor affecting the prognosis of patients with lung cancer." (PMID 34553845, 2022). "When GSDME is highly expressed, both Cisplatin and Paclitaxel can activate caspase-3 to cut GSDME, and transform the cell death pathway from apoptosis which induced by traditional chemotherapy drugs to pyroptosis, and inhibit the proliferation of lung cancer cells." (PMID 33133646, 2020). "Treatment of lung cancer cells with inhibitors of KRAS, EGFR or ALK results in caspase-3-regulated activation of GSDME, thereby increasing the anticancer efficacy of these drugs." (PMID 36920176, 2023). "Moreover, we found that GSDME could serve as a prognostic factor as there was a positive correlation between its expression level and the postoperative survival rate of patients with lung cancer." (PMID 34553845, 2022). "In lung cancer, the absence of GSDME enhances resistance to treatment, while its overexpression augments drug susceptibility." (PMID 38304430, 2024). "Our previous study proved that the ROS generated by NTP could effectively initiate GSDME-dependent pyroptosis in lung cancer cells, showing the potential of NTP in lung cancer treatment." (PMID 38347507, 2024). "To further investigate whether GSDME suppresses the growth of human lung cancer cells, we knocked down GSDME by transfecting NSCLC cancer cells with GSDME-specific siRNA and evaluated cell proliferation." (PMID 37085908, 2023). "Through the analysis of immunohistochemical staining of pathological sections of tissues from 100 patients with lung cancer, we found that the expression level of GSDME in lung cancer tissues was relatively higher than that in the adjacent normal tissues." (PMID 34553845, 2022). "GSDMD or gasdermin-E (GSDME) in human B leukemic cells can be activated by chimeric antigen receptor T cell-released granzyme B and activated GSDMD is required for an optimal cytotoxic T lymphocyte response to lung cancer cells." (PMID 35619176, 2022). "Furthermore, GSDME-WT cancer cells develop tumors of comparable size to that of the GSDME-KO cells in colon cancer and lung cancer models, demonstrating that GSDME may not be involved in tumorigenesis." (PMID 34298833, 2021).
colorectal cancer (55 papers, 2012 to 2026). A primary or metastatic malignant neoplasm that affects the colon or rectum. "Although a few studies have explored the association between GSDME and radiosensitivity, evidence suggests that GSDME-mediated pyroptosis occurs in colorectal cancer cells following radiation exposure." (PMID 40256765, 2025). "Previous studies reported that GSDME-mediated pyroptosis promoted colitis-associated colorectal cancer by releasing HMGB1, which in turn induced tumor cell proliferation via ERK1/2 pathway." (PMID 39789615, 2025). "In colitis-associated colorectal cancer, the GSDME protein levels were significantly higher than those in healthy controls." (PMID 39526199, 2024). "Another recent study discovered that lnc-NEAT1 accelerates ionizing radiation-caused pyroptosis through the miR-448/GSDME pathway in colorectal cancer cells." (PMID 38016064, 2023). "For example, GSDME-mediated pyroptosis contributes to tumorigenesis and promotes tumor progression in colitis-associated colorectal cancer through the release of HMGB1." (PMID 38066523, 2023). "In the colitis-associated colorectal cancer model, the GSDME-/- mice showed colon shortening, reduced weight loss, and decreased tumor size compared to their WT littermates." (PMID 38016064, 2023). "Although its knockout affects the signaling pathways in acute myeloid leukemia and colorectal cancer, many studies are still needed to confirm the association of GSDME-related hearing loss with the development of cancer and protection from cancer." (PMID 36350814, 2022). "GSDME-regulated pyroptosis promotes intestinal inflammation, which plays a role in the development of colitis-associated colorectal cancer." (PMID 35677444, 2022). "However, several studies have reported that GSDME-mediated pyroptosis paradoxically promotes the progression of colitis-associated colorectal cancer." (PMID 39526199, 2024). "Furthermore, GSDME-mediated pyroptosis can promote the occurrence and progression of colitis-associated colorectal cancer by releasing damage-associated molecular pattern molecules and high mobility group box 1 (HMGB1)." (PMID 39526199, 2024). "Increased expression of GSDME has been linked to enhanced pyroptotic activity, and it may contribute to the inflammatory response associated with colorectal cancer progression." (PMID 38066523, 2023). "Additionally, GSDME-knockout mice exhibit protection against radiation-induced weight loss and tissue damage, indicating the influence of GSDME on colorectal cancer radiosensitivity and radiation-related toxicity to surrounding normal tissues through pyroptosis." (PMID 40256765, 2025). "Our findings suggest that P. aeruginosa can act as a potent inducer of immunogenic pyroptosis in colorectal cancer, promoting caspase-3-mediated GSDME cleavage, ROS generation, and DAMP release." (PMID 41484455, 2026). "In this study, we investigated the ability of P. aeruginosa to induce GSDME-mediated pyroptosis in murine colorectal cancer cells and examined its downstream effects on the tumor immune microenvironment." (PMID 41484455, 2026). "IR700DX-6T, a mitochondria-targeted PS, induces GSDME-dependent pyroptosis in colorectal cancer cells." (PMID 40691738, 2025). "In contrast, GSDME appears to be a tumor suppressor gene, with its expression silenced by promoter methylation in gastric-, breast- and colorectal cancers." (PMID 40691738, 2025). "The expression of GSDME also determined radiosensitivity in colorectal cancer and nasopharyngeal carcinoma." (PMID 40256765, 2025). "BI 2536 75 is also used to induce pyroptosis in GIT cancers such as colorectal cancer via caspase-3/GSDME activation." (PMID 39316325, 2025). "They found that radioresistant colorectal cancer cells had low levels of GSDME, while the adjacent tissues demonstrated high GSDME expressions." (PMID 39398428, 2024).
colorectal cancer (continued). "GSDME has been recently declared to inhibit tumor progression in breast, gastric and colorectal cancer by activating antitumor immunity." (PMID 37085908, 2023). "GSDME was identified in several screens for genes methylated in gastric cancer, colorectal cancer and breast cancer." (PMID 37085908, 2023). "Nevertheless, GSDME promoter methylation was higher in colorectal cancer cases characterized by lymphatic vessel invasion and high tumor-node-metastasis (TNM) stage." (PMID 38066523, 2023). "Compared with the WT group, our GSEA results indicated that GSDME knockout upregulated acute myeloid leukemia, colorectal cancer, JAK/STAT signaling pathway, and hedgehog signaling pathway." (PMID 36350814, 2022). "Researches have shown the potential of the methylation status of GSDME as a marker for cancer detection in breast and colorectal cancer." (PMID 35321945, 2022). "Found that gasdermin E (GSDME) can promote the occurrence of colorectal cancer by mediating the pyroptosis of intestinal epithelial cells and releasing HMGB1." (PMID 35923703, 2022). "Analysis of promoter methylation patterns in colorectal cancer (CRC) cell lines identified GSDME as a tumor suppressor for colon cancer." (PMID 35677444, 2022). "GSDME, a candidate tumor suppressor, affects cancers such as breast cancer, gastric cancer, melanoma, and colorectal cancer." (PMID 35677444, 2022). "GSDME is also mainly expressed in epithelial cells in the intestine, and relative to normal tissue, GSDME expression in gastric and colorectal cancer is epigenetically suppressed by methylation." (PMID 36505474, 2022). "It was reported that GSDME-mediated pyroptosis triggered the release of HMGB1, leading to the development of colitis-associated colorectal cancer (CAC) via the activation of ERK1/2 signaling pathway." (PMID 36267972, 2022). "We previously reported that GSDME methylation is a potential biomarker for the diagnosis of breast and colorectal cancers." (PMID 31752152, 2019). "Thus, we propose that NE expressed by ADVNE and PPE expressed by ADVPPE activate Caspase-3 in colorectal cancer cells, which in turn cleaves GSDME to release N-GSDME, thereby inducing pyroptosis and increasing HMGB1 release." (PMID 40082916, 2025). "In colorectal cancer, BI 2536 75 is used to induce pyroptosis via caspase-3/GSDME activation." (PMID 39316325, 2025). "The expression of GSDME makes radiation-resistant colorectal cancer cells sensitive to radiation." (PMID 40026444, 2025). "For example, Triptolide inhibited head and neck cancer cell progression by inducing Gasdermin E (GSDME)-mediated cell pyroptosis 35, GSDME mediated lobaplatin-induced colorectal cancer cell pyroptosis downstream of ROS/JNK/Bax-mitochondrial apoptosis pathway and caused caspase-3/-9 activation." (PMID 38434972, 2024). "Why is GSDME highly expressed in some tumors, such as HCC and colitis-associated colorectal cancer?" (PMID 39526199, 2024). "GSDME expression was found to be upregulated in colorectal cancer." (PMID 38066523, 2023). "In addition to its necrotic activity, GSDME has been proposed to possess tumor suppressor activity in gastric, breast and colorectal cancer." (PMID 37085908, 2023). "However, the death of tumour cells via pyroptosis is often dampened by epigenetic silencing of GSDME, as hypermethylation of GSDME promoter is found in about 52%–65% of primary cancers including colorectal cancer and GC." (PMID 35517821, 2022). "In colorectal cancer, GSDME might be a positive regulator in cell invasion and metastasis through cell migration and angiogenesis, while GSDMA, GSDMB and GSDMD might be a negatively regulator of cell migration." (PMID 35164740, 2022). "Though our analysis, we found that GSDMA, GSDMB, GSDMD and GSDME might be involved in colorectal cancer cell invasion and metastasis, and the former three might played as negative regulators while the last one played as a positive regulator." (PMID 35164740, 2022).
colorectal cancer (continued). "In primary gastric and colorectal cancers, GSDME is inhibited by methylation." (PMID 34553845, 2022). "In addition, in primary gastric cancer and colorectal cancer, GSDME can be suppressed by methylation." (PMID 34305590, 2021). "Identification of promoter hypermethylation and silencing of GSDME expression in colorectal cancer (CRC) suggests GSDME may function as a potential tumor suppressor for colon tumorigenesis." (PMID 33033617, 2020). "GSDME could be one of several tumor suppressor genes that are differentially activated between left‐ and right‐sided colorectal cancers leading to differences in prognosis and survival." (PMID 30993897, 2019). "The effect of GSDME on tumorigenesis was studied both in a chemically induced and in a genetic intestinal cancer mouse model, as strong evidence shows that GSDME plays a role in human colorectal cancer and representative mouse models for intestinal cancer are available." (PMID 31434357, 2019). "In addition, GSDME expression was significantly downregulated, both in colon cancer samples and in colorectal cancer cell lines." (PMID 31434357, 2019). "Our results suggest that GSDME is a promising biomarker for the detection of colorectal cancer." (PMID 30993897, 2019). "In colorectal cancer (CRC), irradiation can induce GSDME-mediated pyroptosis and overexpressing GSDME sensitizes CRC cells to irradiation and increases NK cells infiltration in TME to enhance anti-tumor immunity." (PMID 38323315, 2024). "GSDME-mediated pyroptosis can promote the release of high-mobility group box-1 (HMGB1) to induce the proliferation of tumor cells and the development of colorectal cancer." (PMID 37313458, 2023). "Consistent with the favorable effects of TNFAIP1 on caspase 1/3/7 activity in macrophages or colorectal cancer cells, we found that TNFAIP1 promoted caspase-3 cleavage and subsequent generation of the N-terminal fragment of GSDME both in vitro and in vivo." (PMID 38102610, 2023). "In addition, Rhein 9 has exhibited pyroptotic activity in colorectal cancer (CRC) through the activation of caspase-1 and GSDME." (PMID 39316325, 2025). "A recent study has revealed that GSDME is required for radiation-induced pyroptosis in cancer cells via the CASP3 pathway and that its expression increases the sensitivity of radioresistant colorectal cancer cells." (PMID 35964070, 2022). "The colorectal cancer cell line HCT116 was chosen because it expresses high levels of GSDME but not GSDMD." (PMID 32332857, 2020). "In humans, GSDME is normally expressed in the placenta, heart, brain, and kidneys; however, in mice GSDME is expressed in the cochlea, thymus, colon, lung, brain, spleen, and small intestine, but not in the breasts, gastric system, or colorectal cancer due to hypermethylation of its promotor." (PMID 34867412, 2021).